IFNAR1 (interferon alpha and beta receptor subunit 1)
Diseases named in the same sentence as IFNAR1 in open-access papers (continued):
Sharing a sentence is not in itself a finding about the gene and the disease.
infection (continued). "Investigation of the physiological consequence of IFNAR1 degradation and importance of ORF54 during MHV-68 in vivo infection demonstrates that ORF54 has an even greater impact on persistent infection than on lytic replication." (PMID 21998588, 2011). "By 9 days post-infection, the inflammation continued to increase in STAT1−/− mice while lung inflammation was subsiding in 129 WT, IFNAR1−/− and IFNGR−/− infected mice." (PMID 20386712, 2010). "In situ hybridization was performed on lungs from 129 WT, IFNAR1−/−, IFNGR−/− and STAT1−/− mice harvested at days 2, 5, and 9 post-infection." (PMID 20386712, 2010). "Serum concentration of cytokines following infection was measured and compared to the mock group, as well as between groups receiving anti-IFNAR1 mAb or not." (PMID 41532622, 2026). "A mouse infection model indicated that the absence of IFNAR1 enhances the survival rates of mice infected with M. tuberculosis." (PMID 40137714, 2025). "Inhibition of lysosomal degradation by BafA1, which was added to the cells for 6 hours beginning 18 hours post-infection, partially rescued levels of IFNAR1 and fully rescued levels of IFNGR1 without significantly impacting viral N levels." (PMID 40558091, 2025). "However, in Ifnar1-knockout (KO) mice infected with MCMV, pDCs were still highly resistant to infection." (PMID 38777879, 2024). "This indicates whether the engagement of IFNAR1 happens before NS5 production; these cells are fully competent to deal with the infection." (PMID 38384473, 2024). "More importantly, Ifngr1-/- mice, but not WT or Ifnar1-/- mice, developed an eschar lesion at the infection site starting from day 6 p.i.." (PMID 38743761, 2024). "In contrast, the addition of 1 uM and 10 uM of C-PTIO was sufficient to increase the susceptibility of Ifnar1-/- and Il1r1-/- BMDMs, respectively, while adding any amount of C-PTIO did not impact the course of infection in DKO BMDMs." (PMID 38603763, 2024). "We further demonstrated that administration of loxapine succinate to HAV-infected Ifnar1-/- mice (which lack the type I interferon receptor) results in decreases in the levels of fecal HAV RNA and of intrahepatic HAV RNA at an early stage of infection." (PMID 38478584, 2024). "To test this idea, we inoculated Xcr1-Cre+Ifnar1fl/fl mice with RRV-gp33; DC1s from these mice specifically lacked IFNAR1 expression and were more susceptible to RRV infection than Cre– littermate controls." (PMID 39535221, 2024). "Knock-out of IFNAR1 resulted in a roughly two-fold increase in infection over the non-targeting control compared to the 4- to 5-fold increase observed in the CPSF6 knock-out cells." (PMID 39678349, 2024). "As expected, Il1r1-/- mice were unable to control wt Mtb infection, with elevated lung burden at 14- and 30-days post-infection (dpi), relative to C57BL/6 (B6) mice, whereas loss of Ifnar1 alone has no impact on Mtb burden." (PMID 38603763, 2024). "To develop an alternative mouse model for vaccine testing, we treated adult wild-type mice with MAR1-5A3—an IFNAR1-blocking, non-cell-depleting antibody—prior to infection with the DENV2 strain D2Y98P." (PMID 37112795, 2023). "These mice are treated with an anti-IFNAR1 antibody to suppress but not ablate the type I IFN response to mimic human infection." (PMID 37796973, 2023). "Consistent with our screen and in contrast to the observations with separate cultures, we found that IFNAR1-disrupted cells in this context exhibited a clear competitive advantage over control cells during SARS-CoV-2 infection but not during mock infection." (PMID 36909579, 2023). "Moreover, L. major produces casein kinase 1 (L-CK1) to phosphorylate IFNAR1 on Ser535, leading to the degradation of IFNAR1 and subsequent attenuation of type I IFN signaling during infection." (PMID 36839591, 2023).
infection (continued). "Instead, we found that the fitness advantage of IFNAR1-disrupted cells during SARS-COV-2 infection was mediated by an increase in cell proliferation between days 4 and 8 post-infection, a finding that was mirrored by the antiproliferative response of uninfected cells to exogenous β-IFN treatment." (PMID 36909579, 2023). "The absence of IFNAR1 expression on B cells did not lead to any notable improvements in the clearance of Cl 13 infection." (PMID 37766322, 2023). "Pretreatment with IFN-α2B for 16 hours before HSV-1 infection significantly decreased viral replication levels relative to untreated cells 72 hours after infection in healthy control cells, but not in STAT2-, IFNAR1-, STAT1-, and IRF9-deficient cells." (PMID 36976641, 2023). "We thus identified several alternative inflammatory genes whose expression was either completely (Cxcl1) or partially (Ccl2 and Il6) independent of IFNAR1 signaling following infection." (PMID 38011306, 2023). "Infection-related safety data of anti-BAFF and anti-IFNAR1 from large RCTs." (PMID 36119023, 2022). "This may explain the observation in this study that expression of IRF7 in KO IFNAR1 cells promotes the expression of IFIT5 and IRF1 at the later stage of infection." (PMID 35891486, 2022). "Finally, early inhibition of IFN signaling with anti-IFNAR1 antibodies during MCoV infection, after OM-85 treatment, increased viral loads and persistent activation of IFN-related pathways at day 4 post-infection." (PMID 36479289, 2022). "Using the MHV68 model, however, it was found that global IFNAR1 expression attenuates acute MHV68 replication, promotes host survival, and suppresses persistent MHV68 replication and reactivation during long-term infection, particularly in the peritoneal cavity." (PMID 35968944, 2022). "To determine if signaling through the IFNα/β receptor (IFNAR) is protective during a non-lethal infection with MHV-1, we used an anti-IFNAR1 blocking antibody to prevent IFNα/β-mediated responses." (PMID 35711419, 2022). "No or minor dermal lesions appeared at the site of infection in WT, single mutant Tlr4-/-, Ifnar1-/-, or Ifngr1-/- C57BL/6J mice or CD-1 mice." (PMID 34423779, 2021). "Since CCHFV induced a rapid type I IFN response in WT mice and we have previously demonstrated that Ifnar1-/- mice infected with CCHFV Hoti succumb to the infection, we sought to determine if type I IFN was similarly required to survive MA-CCHFV infection." (PMID 33416494, 2021). "In cells with IFN stimulation, cells in both latency and reactivation group infected with ΔmiRNA HCMV had obviously higher IFNAR1 expression levels than those infected with WT HCMV, indicating the biological function of miRNAs during quiescent infection and viral recurrence." (PMID 33746965, 2021). "Upon PbA-infection the proportion of CCL5+ monocytes vanished, so that CD8+ T cells (17.8%), CD4+ T cells (16.8%) and eosinophils (16.7%), together with M2-like macrophages (9.2%) were the main CCL5 producers in spleens of PbA-infected Ifnar1-/- mice." (PMID 34659202, 2021). "The impaired upregulation of GzmB that we observed in Ifnar1-/- NK cells also occurs during non-lethal infection with mouse cytomegalovirus." (PMID 34015056, 2021). "Previously we showed that EV-A71 infection did not alter the expression of IFNAR1 or JAK1, neither did it induce the degradation of STAT1 or STAT2." (PMID 34992585, 2021). "Unexpectedly, this difference in survival rates between Irf9-/- and Ifnar1-/- mice was not reflected by the bacterial load of the liver and spleen three days post-infection." (PMID 34237114, 2021). "We report that intradermal infection of mice lacking both interferon receptors (Ifnar1-/-;Ifngr1-/-) with as few as 10 R. parkeri elicits eschar formation and disseminated, lethal disease." (PMID 34423779, 2021).
infection (continued). "We find that Sca2 is not required for intracellular survival in organs upon i.v. infection of Ifnar1-/-;Ifngr1-/- mice, but rather, is required for dissemination from skin to internal organs and lethality upon i.d. infection." (PMID 34423779, 2021). "WT but not Ifnar1-/- infected iMOs also trended to upregulate MHC-I after infection, but the differences were not significant (bottom)." (PMID 34015056, 2021). "At 24 h post-infection with J2315, WT BMDMs showed pronounced cleavage of both Caspase-1 and Gasdermin-D, which was either absent or reduced in Casp1/11-/- and Ifnar1-/- BMDM, respectively." (PMID 33684179, 2021). "In contrast, cells lacking either the type I IFN receptor (Ifnar1-/-) or MAVS failed to induce ISG expression upon infection and supported increased viral replication, indicating a dependence on RLR and type I IFN signaling for viral control." (PMID 32330200, 2020). "Influenza A was also shown to downregulate IFNAR1 and IFNAR2 in human monocyte-derived macrophages, however ex vivo infection of human lung tissue with Influenza A only reduced the expression of IFNAR1, but not IFNAR2." (PMID 31935222, 2020). "The results showed the mean percentage of infected cells reached 87.2% upon 2280 infection at an MOI of 1 at 16 hpi, and the surface expression of IFNAR1 but not IFNAR2 was significantly downregulated by nearly 24% upon FCV 2280 infection." (PMID 33075108, 2020). "Plasmacytoid dendritic cells from IRF7-deficient patients produced no type I IFN on infection with SARS-CoV-2, and TLR3−/−, TLR3+/−, IRF7−/−, and IFNAR1−/− fibroblasts were susceptible to SARS-CoV-2 infection in vitro." (PMID 32972995, 2020). "During infection with the infectious bursal disease virus (IBDV), IFNAR1 was also upregulated in DF1 cells and the IBDV replication could be prompted through the negative regulation of CK1α on the abundance of IFNAR1." (PMID 32245514, 2020). "Consistent with the microarray, protein levels of GBP2 and GBP5 were reduced in the Ifnar1−/−, Irf9−/−, Irf1−/−, Trif−/−, and Irf3−/−Irf7−/− macrophages that undergo extensive cell-cell fusion during infection but not in Myd88−/−." (PMID 32150572, 2020). "Instead, blockade of IFNβ but not IFNα improved splenic architecture, decreased infection of CD8α− DC, and enhanced antiviral T cell responses that led to clearance of persistent virus, mimicking many of the effects seen with IFNAR1 blockade." (PMID 33408718, 2020). "Studies investigating USUV vaccines or therapeutics are limited to one study evaluating the efficacy of a USUV vaccine in Ifnar1-/- mice and two studies investigating the use of antivirals in USUV infection, suggesting a need for additional research into these areas." (PMID 33044987, 2020). "Type I IFN plasma concentrations and IFNAR1/2 transcripts are positively correlated to viral load, which is in line with previous studies in DENV and chronic HIV and emphasize the role of type I IFN in the control of viral load during infection." (PMID 33391269, 2020). "In contrast to pDC-depleted mice, IFNAR1−/− mice infected i.v. with C. rodentium did not lose weight during infection and there was no dissemination of bacteria into spleen or liver." (PMID 31024525, 2019). "Arg1 was induced, whereas Asl was repressed upon infection, both independent of hepatocyte-intrinsic IFNAR1 signaling." (PMID 31784108, 2019). "To examine the full range of host immune responses to this virus in normal mice, we administered an anti-IFNα/β receptor antibody (anti-IFNAR1) 1 day prior to a single inoculation of ZIKV to BALB/c mice and detected a transient viremia from 2 to 3 days post infection (dpi)." (PMID 31455769, 2019). "Since IFNAR1−/− mice did not lose weight during the course of infection, this suggested that the effect of pDC depletion was not due to lack of type I IFN signaling." (PMID 31024525, 2019). "We again added a blocking anti-Ifnar1 mAb to OVX WT and Ifnlr1−/− mice to facilitate infection." (PMID 30655513, 2019).
infection (continued). "Infection of Ifnar1-/- mice lacking the type I interferon receptor, but not congenic wild-type animals, resulted in uniformly fatal disease 6 to 10 days after infection." (PMID 31194854, 2019). "Similarly, the protein level of IFN-β and IFNAR1 was also significantly high in the lungs and spleen tissue of M. bovis infected mice than PBS controls at both 21 and 84 days post-infection." (PMID 31801478, 2019). "In Ifnar1 knockout mouse spinal cord and dorsal root ganglia-derived cultures as well as in a patient who died of Zika-GBS, PNS neurons and Schwann cells appear rather refractory to infection." (PMID 30050403, 2018). "In contrast, robust EMH was observed in the spleens of Ifnar1-/- mice, corresponding to increased mature myeloid cells, demonstrating IFNα/β suppress hematopoiesis systemically during IOE infection." (PMID 30080899, 2018). "In this study, we found that the self-healing course of infection seen in L. major-infected C57BL/6 WT animals was fully preserved in C57BL/6 mice lacking the IFN-β-gene or a functional type I IFN receptor (IFNAR1−/−)." (PMID 29459858, 2018). "In line with the clinical findings, C57BL/6 IFN-β−/−, IFNAR1−/−, and WT mice exhibited similar mRNA expression levels of IFN-γ, interleukin (IL)-4, IL-12, IL-13, inducible nitric oxide synthase, and arginase 1 during the acute and late phase of the infection." (PMID 29459858, 2018). "More striking was the nearly twenty-fold increase in the proportion of dead and dying cells (7-AAD+) among the HSPC pool in WT mice, whereas Ifnar1-/- mice exhibited no such increase at day 7 post-infection." (PMID 30080899, 2018). "Of note, 129/Sv‐IFNAR‐1−/− mice were not resistant to LDV infection as their lactate dehydrogenase serum titer was similar to that of control 129/Sv‐infected mice (data not shown)." (PMID 28474504, 2017). "In contrast to WT animals, Ifnar1 −/− mice were not protected against infection post vaccination with CDA + OVA." (PMID 28754303, 2017). "Occasional neurones, Schwann cells and macrophages (as assessed by positive staining for NeuN, S100 and F480 respectively) appeared ZIKV +ve at 72 hpi following infection with ZIKV at MOI 3.0, however the overall levels of infection were barely above background levels, even in Ifnar1 KO cultures." (PMID 28645311, 2017). "Histopathology from the cecum extracted at 8 dpi illustrates that WT and Ifnar1-/- mice develop severe inflammation 72 h after infection with S. Typhimurium, whereas no abnormalities are seen after PR8 or mock infection." (PMID 27149619, 2016). "Our findings, however, uncovered a significant blooming of Proteobacteria at day 9 after PR8 infection only in the WT mice, whereas no significant increase was noted in the Ifnar1-/- mice, irrespective of the infection." (PMID 27149619, 2016). "The small number of transcripts shown to be perturbed in the blood and tissue of Ifnar1-/- as compared to WT mice in the absence of infection were shown a cohort of genes dependent on IFNαβR signaling." (PMID 26918359, 2016). "In contrast, infection with PR8 did not enhance S. Typhimurium gut colonization in the Ifnar1-/- mice." (PMID 27149619, 2016). "Changes in gene expression were also seen in the blood of the Ifnar1-/- as compared to WT mice in the absence of infection (approximately 25%), suggesting that type I IFN signaling is already evident in uninfected mice." (PMID 26918359, 2016). "Mice lacking the IFN-I receptor (IFNAR1-/-) failed to clear a primed Cl13 infection confirming that the early IFN-I signaling is required for early clearance." (PMID 25569216, 2015). "We cannot exclude the possibility that the lack of such tonic signals in Ifnar1−/− mice contributes to infection-related phenotypes of these animals." (PMID 23840314, 2013).
infection (continued). "We first investigated the overall lung permeability in infected and uninfected Ifnar1+/+ and Ifnar1−/− mice by i.v. injection of FITC-labelled albumin, followed by analysis of FITC-albumin leakage into the alveolar space 16 hours after infection." (PMID 24244159, 2013). "Both IFNα and IFNβ are recognized by a heterodimeric receptor composed of the two subunits IFNAR1 and IFNAR2, and in general promote an anti-inflammatory response during infection, for example by reducing the production of pro-inflammatory cytokines IL-1 and TNFα." (PMID 24244159, 2013). "Consistent with published data the absence of Ifnar1 strongly reduced the number of apoptotic cells in extra-follicular areas of the white pulp after i.p. infection." (PMID 23840314, 2013). "Some of these molecules (IRF7, IRF9, STAT1, STAT2) are known ISGs and were upregulated in wild-type but not in IFNAR1−/−IL-28Rα−/− epithelia at 24 hours post infection." (PMID 24278020, 2013). "Infected MAVS−/− and IRF3−/−IRF7−/− epithelia show ISG induction in the absence of any detectable IFN upregulation, while IFNAR1−/−IL-28Rα−/− cells, which produce but cannot respond to IFNs, did not express ISGs in response to infection." (PMID 24278020, 2013). "Strikingly, Kim-1 expression levels peaked at day 3 of infection and were much higher in WT mice when compared to mice lacking IFNAR1." (PMID 22911155, 2012). "At day 3 post infection, the induction of monocyte-attracting chemokines was strongly reduced in absence of IFNAR1 signaling." (PMID 22911155, 2012). "The cooperative nature of the strategy is evident by the lack of IFNAR1-dependent inhibition of ISREΔ replication we observe late in acute infection, which correlates with increased lethality in a moderately immune compromised (IFNγ-/-) host." (PMID 22114555, 2011). "Our results suggest that signaling via the IFNαβ receptor in neonatal mice results in the robust induction of at least a subset of ISGs and interferon-induced serum proteins, and that the absence of IFNAR1 results in exacerbated infection and rapid death." (PMID 22028657, 2011). "The infectivity of SARS-CoV-2 Omicron BA.1 in mice lacking the hACE2 receptor opened the possibility to investigate the impact of other host factors on the infection of SARS-CoV-2 such as the lack of type I IFN responses using the interferon-alpha receptor-1 (IFNAR1) knockout mice." (PMID 38742107, 2024). "As an example, during infection, PERK may antagonize IFN sensing by supporting IFNAR1 degradation." (PMID 39100663, 2024). "In the current study, we showed that in the absence of IFNAR1 signalling, PD-L1 was required for survival by preventing an overexuberant inflammatory response in the lung, while blockade of PD-L1 during later stages of infection had no adverse effect." (PMID 38543756, 2024). "After anti-IFNAR1 treatment, the Venus protein signal increased in several myeloid cells in the DLN, including both DC1s (CD11c+ MHC-II+ Xcr1+) and DC2s (CD11c+ MHC-II+ Sirpα+), although we cannot definitively distinguish direct infection from phagocytosis of infected cells using this assay." (PMID 39535221, 2024). "However, in vitro infection employing Ifnar1 KO intestinal epithelial cells showed no changes in C. parvum attachment/invasion or epithelial cell antiparasitic defense." (PMID 36928642, 2023). "Alternatively, type I IFN signalling can be transiently suppressed in wild-type mice using the IFNAR1-blocking, non-cell-depleting monoclonal antibody MAR1-5A3, which has been shown to render them susceptible to infection with low-passage clinical isolates of WNV, ZIKV, and DENV1." (PMID 37112795, 2023). "While the timing of anti-IFNAR1 antibody treatment and ZIKV inoculation was consistent between mice, the embryonic stage at the time of these treatments and inoculation could affect the kinetics of infection and transmission to the fetus." (PMID 37796973, 2023).